RN7SKP25 (RN7SK pseudogene 25)
Gene: Miscellaneous RNA gene on chromosome 3 (142,673,597 to 142,673,904, forward strand). Ensembl gene ENSG00000199319.
Homologues: Orthologues: chimpanzee 7SK (93% identical). Paralogues in human: RN7SKP9 (78% identical), 7SK (78% identical), RN7SKP203 (78% identical), RN7SKP78 (77% identical), RN7SKP255 (76% identical), RN7SKP180 (76% identical), RN7SKP71 (76% identical), RN7SKP184 (75% identical), RN7SKP296 (75% identical), RN7SKP79 (75% identical), RN7SKP80 (75% identical), RN7SKP90 (75% identical), and 283 more.